USP33 (ubiquitin specific peptidase 33)
Diseases named in the same sentence as USP33 in open-access papers (continued):
Sharing a sentence is not in itself a finding about the gene and the disease.
infection (3 papers, 2018 to 2024). The state of being infected such as from the introduction of a foreign agent such as serum, vaccine, antigenic substance or organism. "More importantly, we successfully delivered siRNAs targeting USP33 to the lungs of mice using LNPs, which effectively attenuated viral replication and virulence in a mouse infection model." (PMID 39301916, 2024). "Moreover, we constructed stable cell lines with USP33 KO in A549‐ACE2 and Calu3 cells, and the viral load in USP33‐KO cells at different time points after infection was reduced compared to that in control cells." (PMID 39301916, 2024). "However, the transcriptomic data from whole blood showed higher mRNA levels of USP33 in patients who developed mild and severe disease after infection compared to the healthy individuals." (PMID 39301916, 2024). "As the virus causes acute infections, clinical symptoms in infected patients usually present within 1–3 days of infection, making this strategy sufficient to alleviate most infections and reduce the potential for side effects from prolonged suppression of USP33." (PMID 39301916, 2024). "This indicates that the high expression of USP33 is one of the causes of more severe disease rather than a result of infection." (PMID 39301916, 2024). "To confirm the facilitating effect of USP33 on viral replication under actual infection conditions, we selected two lung‐related cell lines, Calu3 and A549‐ACE2, and constructed corresponding cell lines stably overexpressing USP33." (PMID 39301916, 2024).
neurodegenerative disease (1 paper, 2025). A disorder of the central nervous system characterized by gradual and progressive loss of neural tissue and neurologic function. "The involvement of other DUBs such as USP14, USP15, and USP33 further complicates the landscape of neurodegenerative diseases." (PMID 39840724, 2025). "The strategic inhibition of USP33 emerges as a novel therapeutic strategy, further expanding the potential avenues for managing neurodegenerative diseases." (PMID 39840724, 2025).
USP33 also shares sentences with these, for which no sentence is quoted: laryngeal squamous cell carcinoma (2 papers); acute coronary syndrome (1); acute lymphoblastic leukaemia (1); acute myeloid leukemia (1); heart failure (1); lung squamous cell carcinoma (1); melanoma (1); ovarian carcinoma (1); pulmonary tuberculosis (1); thymoma (1).